EIPR1 (EARP complex and GARP complex interacting protein 1)
Description:
Acts as a component of endosomal retrieval machinery that is involved in protein transport from early endosomes to either recycling endosomes or the trans-Golgi network. Mediates the recruitment of Golgi-associated retrograde protein (GARP) complex to the trans-Golgi network and controls early endosome-to-Golgi transport of internalized protein. Promotes the recycling of internalized transferrin receptor (TFRC) to the plasma membrane through interaction with endosome-associated recycling protein (EARP) complex. Controls proper insulin distribution and secretion, and retention of cargo in mature dense core vesicles (By similarity). Required for the stability of the endosome-associated retrograde protein (EARP) complex subunits and for proper localization and association of EARP with membranes (By similarity).
Synonyms: TSSC1; EIPR-1
Tractability: PROTAC: ubiquitination databases record sites on it.
Gene: Protein-coding gene on chromosome 2 (3,188,925 to 3,377,852, reverse strand). Ensembl gene ENSG00000032389.
Subcellular location: Golgi apparatus, trans-Golgi network
Subcellular location (Human Protein Atlas): Nucleoli; Nucleoplasm; Intermediate filaments
Gene Ontology:
Molecular function: protein binding
Biological process: positive regulation of endocytic recycling; positive regulation of retrograde transport, endosome to Golgi; endocytic recycling; regulation of insulin secretion; regulation of transport
Cellular component: EARP complex; GARP complex; nucleolus; nucleoplasm; trans-Golgi network; Golgi apparatus
Genetic constraint (gnomAD): Loss-of-function variants: 25 observed, 45.94 expected, observed/expected ratio (o/e) 0.54, 90% interval 0.4 to 0.76. The upper end of that interval is the gene's LOEUF score, 0.76, which puts it in group 3 of 6, group 1 being the genes least tolerant of losing a copy. Missense variants: 415 observed, 504.51 expected, observed/expected ratio (o/e) 0.82, 90% interval 0.76 to 0.89. Synonymous variants: 204 observed, 201.92 expected, observed/expected ratio (o/e) 1.01, 90% interval 0.9 to 1.13.
Homologues: Orthologues: chimpanzee EIPR1 (99% identical), dog EIPR1 (94% identical), rat Eipr1 (93% identical), mouse Eipr1 (93% identical), guinea pig EIPR1 (93% identical), pig EIPR1 (88% identical), tropical clawed frog eipr1 (85% identical), zebrafish eipr1 (85% identical), macaque EIPR1 (82% identical), Drosophila melanogaster CG10646 (40% identical), Caenorhabditis elegans eipr-1 (34% identical).
Diseases named in the same sentence as EIPR1 in open-access papers:
EIPR1 is named in the same sentence as 7 diseases in open-access papers, as found by Europe PMC text mining. Sharing a sentence is not in itself a finding about the gene and the disease. The quoted sentences say what the papers report.
insulinoma (1 paper, 2016). "In addition, using a proteomic approach in rat insulinoma cells, we show that EIPR-1 physically interacts with the EARP complex." (PMID 27191843, 2016). "To identify interactors of EIPR-1, we expressed GFP-tagged rat EIPR1 in the rat insulinoma cell line 832/13 and performed mass spectrometry on GFP pulldowns." (PMID 27191843, 2016).
ovarian carcinoma (1 paper, 2023). A malignant neoplasm originating from the surface ovarian epithelium. "One striking example is that of an MHC-bound peptide in an upstream ORF of the EIPR1 gene, supported by peptides from the proteogenomic search in nine ovarian cancer samples." (PMID 37275273, 2023).
tumor (3 papers, 2016 to 2023). "EIPR1 is located in the imprinted gene domain of 11p15.5, an important tumor-suppressor gene region." (PMID 37830558, 2023). "The human Eipr1 gene was originally named Tssc1 for “tumor-suppressing subtransferable candidate 1” because it was first identified as one of several genes thought to be candidates for a tumor-suppressing activity on chromosome 11." (PMID 27191843, 2016). "In addition, FRA1 overexpression upregulated EIPR1 (also known as TSSC1), a tumor-suppressor gene." (PMID 37830558, 2023).
EIPR1 also shares sentences with these, for which no sentence is quoted: breast carcinoma (2 papers); metastatic disease (1); psychiatric disorder (1); Wilms tumor (1).